IL6 (interleukin 6)
Diseases named in the same sentence as IL6 in open-access papers (continued):
Sharing a sentence is not in itself a finding about the gene and the disease.
endotoxemia (continued). "In order to explore the functions of inulin in inflammation and endotoxemia in KO mice, the levels of LPS and inflammatory cytokines, such as TNF-α, IL-6 and IL-1β, were detected." (PMID 33104864, 2021). "Compared to those in the sham group, the plasma levels of LPS, IL6 and TNFα were found to be significantly reduced in the RYGB group, indicating that endotoxemia and systemic inflammation were prominently alleviated by RYGB." (PMID 34290269, 2021). "Demonstrating the predictive power of BMI percentile and plasma glucose levels, we identified baseline cut-off values for IL-6, ICAM and endotoxemia for obese children and adolescents with early vascular damage." (PMID 33924229, 2021). "Given the correlations between inflammatory markers and the BMI percentile, we used an ROC curve analysis to evaluate the predictive power of BMI percentile, plasma glucose level and serum triglycerides on IL-6, ICAM and endotoxemia." (PMID 33924229, 2021). "The results indicated a significant predictive power of BMI percentile on inflammatory markers: IL-6 (AUC = 0.803, 95% CI: 0.72–0.88, p < 0.001), ICAM (AUC = 0.806, 95% CI: 0.72–0.89, p < 0.001) and endotoxemia (AUC = 0.762, 95% CI: 0.68–0.85, p = 0.019)." (PMID 33924229, 2021). "For example, glibenclamide significantly suppresses LPS-induced plasma IL-6 and TNF-α levels in ex vivo endotoxemia mice." (PMID 34776934, 2021). "The results indicated a significant predictive power of BMI percentile on inflammatory markers: IL-6 (AUC = 0.803, p < 0.001), ICAM (AUC = 0.806, p < 0.001) and endotoxemia (AUC = 0.762, p = 0.019)." (PMID 33924229, 2021). "In general, many additional pro-inflammatory mediators controlled by NF-κB p65 are known (e.g., TNF-α, IL-1β, IL-6 and MCP-1) and their contribution to the observed effects of Aqp9 deletion on the survival to endotoxemia can be anticipated." (PMID 33670755, 2021). "So, this finding agrees well with the effects of SM on the production of IL-6 and TNF-α observed in the LPS-induced endotoxemia model." (PMID 33114200, 2020). "During experimental endotoxemia, PCSK–9 knock-out mice produced significantly lower levels of pro-inflammatory cytokines, including interleukin-6 (IL–6) and tumor necrosis factor–α (TNF–α)." (PMID 32796672, 2020). "Additional studies using iron chelation in endotoxemia models also showed a decrease in LPS-induced activation of NF-κB and reduced plasma levels of TNF-α, IL-6, IL-1β and IL-10." (PMID 32466384, 2020). "Firstly, we measured the serum levels of IL-6, TNF-α, and IL-1β to confirm the successful establishment of the endotoxemia model." (PMID 32894042, 2020). "Here, our results show that blockade of BAFF activity suppresses systemic and local inflammation, characterized by decreased serum and intestinal IL-1β, IL-6, and TNF-α levels, in LPS-induced endotoxemia." (PMID 33324396, 2020). "We examined serum concentrations of IL-1β, IL-6, TNF-α, and IL-10 to investigate the effect of BAFF antibody on systemic inflammation in endotoxemia." (PMID 33324396, 2020). "The levels of IL-1β, IL-6, and TNF-α in the sera detected by ELISA and the mRNA levels in the cortices detected by qPCR increased dramatically in the endotoxemia mice." (PMID 33192176, 2020). "Using structural equation models, we also tested if the relationship between endotoxemia and cardiometabolic complications was mediated by the latent (unobserved) variable inflammation inferred from the observed biomarkers CRP, TNF-α and IL-6." (PMID 33299020, 2020). "For marker of endotoxemia, serum endotoxin and LBP were measured using TNF-α and IL-6 levels as indices of systemic inflammation." (PMID 31178854, 2019). "To explore the role of ouabain in LPS-induced endotoxemia, we analyzed the production of inflammatory cytokines including TNF-α and IL-6 in C57BL/6 mice." (PMID 31182997, 2019).
endotoxemia (continued). "In a murine endotoxemia model, AWRK6 offered satisfactory protection efficiency against endotoxemia death, and the serum levels of LPS, IL-1β, IL-6, and TNF-α were found to be attenuated using ELISA." (PMID 29463000, 2018). "In a severe model of endotoxemia (induced by 25 mg/kg LPS), TNF, IL-6, and IL-12p40 concentrations in blood and mortality rates (88% in both groups, P = 0.69) were strongly increased, but remained similar in SIRT2+/+ and SIRT2−/− mice." (PMID 28894448, 2017). "To determine if the protective activity of N4 was associated with inflammatory cytokines, we measured the concentrations of interleukin-6 (IL-6), IL-1β, and tumor necrosis factor alpha (TNF-α) in the sera from mice with endotoxemia." (PMID 27795369, 2017). "Researches done in vivo and vitro suggest that endotoxemia increases phosphorylation of Jun N-terminal kinase (JNK), expression of monocyte chemoattractant protein-1 (MCP-1) and IL-6 in muscle and adipose tissues." (PMID 26799617, 2016). "Production of proinflammatory cytokines such as IL-1-β, IL-6, and TNF-α has recently been found in skeletal muscle tissue during special conditions such as endotoxemia." (PMID 25821631, 2015). "A body of animal and clinical trials have shown that DEX decreases cytokine (TNF-α, IL-6) secretion after endotoxin injection and that DEX reduced the mortality rate in endotoxemia-induced shock rat models in a dose-dependent manner." (PMID 26171113, 2015). "Studies of other cytokines and chemokines, including interleukin-6 (IL-6), monocyte chemotactic protein-1 (MCP-1), and keratinocyte chemoattractant (KC), were shown to be increased in kidney during endotoxemia and renal inflammation." (PMID 25799354, 2015). "In line with this notion, the deacetylation-mediated interaction of HMGB1 and SIRT1 in mice was sufficiently potent to robustly protect against endotoxemia in response to LPS challenge by inhibiting the secretion of HMGB1 and cytokines such as TNF-α and IL-6." (PMID 26522327, 2015). "Pretreatment with IL-6 or IL-10 could provide a protection in endotoxemia by inhibiting tissue degradation as it has already been established in our prior studies that pretreatment with IL-6 lowers liver damage in experimental endotoxemia by modulating ROS production and cell infiltration." (PMID 25759837, 2015). "Endotoxemia depresses cardiac function via upregulation of the expression of cardiodepressant cytokines, including TNF-α, IL-1β and IL-6." (PMID 25209241, 2014). "A possible/plausible regulator of this phenomenon is heme oxygenase-1 (HO-1), which is induced by LPS and provides defense against endotoxemia, including LPS-induced ARF, controlling the IL-6/IL-10 balance." (PMID 24376813, 2013). "Endotoxemia led to a rise in body temperature and inflammatory symptom scores and a rise in plasma TNF-α, IL-6, IL-10 and IL-1RA." (PMID 24358337, 2013). "Endotoxemia induced a characteristic cytokine response with high levels of key inflammatory cytokines, such as IL-1β, TNF-α and IL-6, but EP and GL significantly attenuated such responses compared with the con group." (PMID 23497622, 2013). "Since plasmids was found to decrease in vitro production of TNF-α and IL-6 by LPS-stimulated macrophage cell line and these cytokines play a key role in the inflammatory process, we evaluate if low doses of plasmid could have a beneficial effect in vivo in an endotoxemia model." (PMID 23137350, 2012). "To explain the mechanism involved in the plasmid-induced attenuation of MAP drop in LPS-stimulated rats, we determined the gene expression of liver IL-6 and TNF-α and plasma concentration of AVP and NO, key mediators in endotoxemia." (PMID 23137350, 2012). "A GWI Veteran microbiota transplant in humanized mice showed a human microbiome reconstitution and a systemic inflammatory pathology, as reflected by increases in interleukins 1β, 6, 8 (IL-1β, IL-6, IL-8), tumor necrosis factor receptor 1 (TNF R-1), and endotoxemia." (PMID 38892281, 2024).
endotoxemia (continued). "The restoration of intestinal barrier function decreases intestinal permeability, which reduces the concentration of LPS entering the circulation, and reduced endotoxemia leads to decreased serum concentrations of inflammatory cytokines such as TNF-α and IL-6, thereby attenuating CLGI." (PMID 39201665, 2024). "Furthermore, JQ1 has been found to reduce levels of IL-6 and TNF and prevent death in mice induced with LPS-induced endotoxemia." (PMID 38407669, 2024). "During the development of endotoxemia, LPSs bind to toll-like receptor 4 (TLR4) and increase the concentration of inflammatory markers such as IL-1α, IL-6, INF-γ, and TNF-α, and consequently systemic chronic intestinal inflammation may develop." (PMID 39193369, 2024). "When comparing ATB+DSS with P. aeruginosa (ATB+DSS+PA) and ATB+DSS mice, P. aeruginosa exacerbated loose stool in almost all mice, leaky gut parameters (bacteremia, FITC-dextran, and endotoxemia), systemic inflammation (TNF-α, IL-6, and IL-10), and liver damage (alanine transaminase)." (PMID 39546435, 2024). "Of importance was the reduction of IL-6 levels by Pla treatment during LPS-induced endotoxemia, but IL-6 levels were not altered when Pla was given as treatment to mice subjected to CLP." (PMID 36917195, 2023). "The results of our research showed that the administration of MLT to animals with endotoxemia led to a decrease in the level of cytokines TNF-α and IL-6 in the liver tissue compared to the group of animals administered LPS, in which their concentration was significantly increased." (PMID 38203627, 2023). "In CLP alone, the Ezh2 inhibitor attenuated kidney damage (serum creatinine) and serum cytokines (TNF-α, IL-6, and IL-10) but not cell-free DNA, endotoxemia, and bacteremia." (PMID 37239864, 2023). "Moreover, IID activates downstream proinflammatory factors such as IL-6 and TNF-α, which are mainly regulated by NFκB-activated endotoxemia by upregulating the levels of IL-6 and TNF-α, inducing intestinal mucosal injury and chronic inflammatory bowel disease." (PMID 37529040, 2023). "In endotoxemia mice, CPE could decrease IL-6, MCP-1, TNF-α, and PGE2 levels in the serum after a single therapeutic administration, showing a definitely anti-inflammatory activity." (PMID 36238556, 2022). "Collectively, these data display that the SEM18 peptide significantly inhibited TNF-α and IL-1β, but not IL-6, in endotoxemia-treated mouse lung tissues." (PMID 35337084, 2022). "Furthermore, in a rat model of endotoxemia, both compounds reduced TNF-α and IL-6 levels by decreasing NF-κB expression in the lung and liver, in addition to counteracting histopathological changes caused by LPS." (PMID 36364031, 2022). "Endotoxemia mortality results exclusively from a systemic inflammatory response characterized by an acute increase in circulating inflammatory cytokine levels (e.g. TNF, IL-6, and IL-1β) from splenocytes and myeloid-derived innate immune cells." (PMID 36264059, 2022). "Considering the primary role of TNF-α in modulating the expression of IL-1β and IL-6, we hypothesized that TNF-α may have a more immediate role in systemic inflammation and organ injury (e.g., the lungs) in endotoxemia." (PMID 35337084, 2022). "However, in the mice endotoxemia model, as expected, LPS injection indeed upregulated the expressions of TNF-α, IL-1β, IL-6, and MCP-1 mRNA." (PMID 35370629, 2022). "However, with their differential effects on inhibiting IL-6, the present study illustrates that the KCF18 and SEM18 peptides can achieve similar effects on mitigating endotoxemia-induced systemic inflammation and lung injury in mice." (PMID 35337084, 2022). "In addition, both probiotics also attenuated liver enzyme (alanine transaminase), oxidative injury (reduced MDA and increased GSH), serum cytokines (TNF-α, IL-6, and IL-10), and gut leakage (FITC-dextran assay and endotoxemia)." (PMID 35010955, 2021).
endotoxemia (continued). "Moreover, inflammatory markers, IL-6, ICAM 1 and endotoxemia were significantly higher in obese patients versus the control group." (PMID 33924229, 2021). "Endotoxemia, a classical model of systemic inflammation, is characterized by the amplified production of tumor necrosis factor alpha (TNF-α), interleukin-1β (IL-1β), interleukin-6 (IL-6), and nitric oxide (NO) by immune cells and vascular endothelium." (PMID 33430014, 2021). "Thus, inflammatory markers, IL-6, ICAM 1 and endotoxemia, show significantly higher values in pediatric obese patients, leading to chronic and systemic inflammation." (PMID 33924229, 2021). "ROS and RNS induced by oxidative stress may cause tissue damage, and cytokines of TNF-α, IL-1β, and IL-6 can increase the production of ROS and RNS during endotoxemia." (PMID 34065201, 2021). "MV with endotoxemia aggravated VIDD, as demonstrated by increased interleukin-6 and macrophage inflammatory protein-2 levels, oxidative loads, and the expression of HIF-1α, calpain, caspase-3, atrogin-1, muscle ring finger-1, and microtubule-associated protein light chain 3-II." (PMID 33567713, 2021). "Interestingly, compared with LPS treatment group, remimazolam remarkably improved survival rate of endotoxemia mice and decreased the release of LPS-induced inflammatory mediators (such as TNF-α, IL-6, and IL-1β)." (PMID 34867346, 2021). "As expected, compared with the NCD group, the HFD group displayed a significant increase in serum LPS, TNF-α, and IL-6 levels, which was reversed by PEW supplementation, suggesting that PEW might prevent HFD-induced endotoxemia and systemic inflammation." (PMID 32256675, 2020). "Increased levels of wet-to-dry weight ratio; BAL fluid total protein; and IL-6, TNF-α, MIP-2 and VEGF protein production were observed in mice with endotoxemia treated with high-tidal-volume compared with the other MV treatment groups and the nonventilated control mice." (PMID 32353952, 2020). "Our second objective was to test, using structural equation models, if the relationship between endotoxemia and cardiometabolic complications was mediated by the latent (unobserved) variable inflammation inferred from the observed biomarkers CRP, TNF-α and IL-6." (PMID 33299020, 2020). "In a LPS-induced endotoxemia mouse model, a single intraperitoneal injection of Cl-EE (75–300 mg/kg) could lower circulatory TNF-α, IL-6 and MCP-1 levels." (PMID 31842849, 2019). "(2008) believe that a possible mechanism by which Dex inhibits inflammatory response is that Dex regulates cytokine production, as their study shows that Dex can significantly inhibit the production of pro-inflammatory factors such as IL-6 and TNF-α in endotoxemia mice." (PMID 31545916, 2019). "Although endotoxemia was induced in the HFPg mice, no increases in Tnfa or Il6 levels were observed." (PMID 30405551, 2018). "These include low HDL and total cholesterol levels, increased proinflammatory cytokines (IL-1, IL-6, TNF-alpha), endotoxemia (lipopolysaccharide), decreased apolipoprotein A-1 level, and hemorrhage and infarction in the adrenal gland due to proclivity to hemorrhage and thrombosis in cirrhosis." (PMID 29201798, 2017). "This dissemination may induce a bacteremia or endotoxemia that is characterized by increased serum levels of inflammatory mediators such as C-reactive protein (CRP), IL-6, and fibrinogen." (PMID 23497572, 2013). "Likewise, the slow-releasing H2S donor GYY4137, can reduce LPS-induced endotoxemia in mice, as well as the synthesis of pro-inflammatory mediators (such as TNF-α, IL-1β, IL-6, NO and PGE2) by LPS-stimulated RAW 264.7 macrophages in vitro." (PMID 24237604, 2013). "It was found that dexmedetomidine at the doses of 10 and 20 μg/kg decreased CLP-induced pulmonary inflammation and mortality, reduced production of IL-6 and TNF-α in plasma and BALF of septic rats, and suppressed TLR4/MyD88 expression and NF-κB activation in lung of endotoxemia rats induced by CLP." (PMID 23690665, 2013).
endotoxemia (continued). "Experimental observations indicate that IL-22 application in murine endotoxemia fails to significantly affect production of the pro-inflammatory cytokines TNFα, IL-6, and IFNγ analyzed in the early phase (up to 8 h after onset of endotoxemia) of the syndrome." (PMID 23382730, 2013). "We assumed that TNFα, IL-6 and IL-10 form an important fraction of gut derived nonbacterial factors, transported via mesenteric lymph and contributing to lung injury during endotoxemia." (PMID 24356325, 2013). "After detection using ELISA and Western blot assays, it has also been found that propofol can not only promote the expression of Annexin A1, but also inhibit the phosphorylation level of p38 and release of inflammatory factors (IL-1β, IL-6 and TNF-α) in rats with endotoxemia." (PMID 22164217, 2011). "Of note, this subject had a very low cytokine response during endotoxemia (TNF-α level of 169 pg/ml compared with the group mean of 814 ± 133 pg/ml, and IL-6 level of 508 pg/ml compared with the group mean of 1,111 ± 142 pg/ml) and an average cortisol response (0.29 to 0.67 μmol/l)." (PMID 20444270, 2010). "Horses from both experimental groups presented clinical signs and hematological changes in endotoxemia, including an increase in heart rate and body temperature, neutrophilic leukopenia, an increase in serum bilirubin, glucose, lactate, and an increase in TNF-α, IL-6, and IL-10." (PMID 38338117, 2024). "Electrical DMN stimulation significantly reduced pro-inflammatory cytokine levels in the serum (TNF: p = 0.0012; IL-6: p = 0.427) and spleen (TNF: p = 0.0001; IL-6: p = 0.0077), as well as increasing the serum levels of the anti-inflammatory cytokine IL-10 (p = 0.0284) during endotoxemia." (PMID 36918973, 2023). "We assessed the therapeutic efficacy between triple cytokine (tumor necrosis factor-α [TNF-α], interleukin-1β [IL-1β], and IL-6) inhibition (mediated by KCF18 peptide) and single cytokine (TNF-α) inhibition (mediated by SEM18 peptide) on alleviating lung injury in the early phase of endotoxemia." (PMID 35337084, 2022). "Moreover, LA5 improved gut permeability defect (gut leakage) and leaky gut-induced systemic inflammation as indicated by FITC-dextran assay, ZO-1tight junction protein, endotoxemia, colon mucin production (gene expression of muc2) and serum cytokines (TNF-α, IL-6, and IL-10)." (PMID 33737543, 2021). "During endotoxemia, high levels of TNF-α and IL-6 could activate JAK2-STAT3 cascade in CNS." (PMID 31213027, 2019). "However, it warrants further studies to demonstrate whether the production and release of TNF-α, IL-1βand IL-6 is altered in HMGB1/TLR4 signaling pathway and whether this is the main pathological mechanism in endotoxemia induced acute neuro-inflammation." (PMID 28059131, 2017). "However, in the case of incomplete decontamination, a minor degree of reduction in peri- and postoperative endotoxemia was found, which did not fully explain the reduction of IL-6 plasma levels." (PMID 24266958, 2013). "Therefore, we hypothesized that ATF3 may modulate the expression of IL-6 and TNF-α in the early and later stages of endotoxemia." (PMID 24062788, 2013). "Furthermore, our data confirmed that endotoxemia increased the plasma levels of the pro-inflammatory cytokine IL-6 in plasma and the TNF-α renal expression in wild type MORG1+/+ mice while in contrast IL-6 and TNF-α induction were significantly reduced in MORG1+/− mice." (PMID 29402223, 2018). "Clinical trials have shown that GTS-21 intervention in patients with endotoxemia does not lead to substantial differences in the serum levels of the proinflammatory cytokines TNF-α and IL-6 compared to those in controls." (PMID 40337863, 2025). "In comparison with the control, 5 in 7 ATB+DSS mice demonstrated normal stool consistency with systemic inflammation (alanine transaminase, endotoxemia, TNF-α, and IL-6), implying the leaky gut without an overt diarrhea." (PMID 39546435, 2024).